CLEC4G (C-type lectin domain family 4 member G)
Description:
Binds mannose, N-acetylglucosamine (GlcNAc) and fucose, but not galactose, in a Ca(2+)-dependent manner, in vitro. (Microbial infection) Acts as a receptor for Japanese encephalitis virus. (Microbial infection) Acts as a receptor for Ebolavirus. (Microbial infection) Acts as a receptor for SARS-CoV. (Microbial infection) Acts as a receptor for Lassa virus and Lymphocytic choriomeningitis virus glycoprotein.
Synonyms: LSECtin; UNQ431; DTTR431; LP2698
Tractability: Antibody: its Gene Ontology location is reachable by antibodies, with high confidence; UniProt places it where antibodies can reach, with medium confidence; UniProt predicts a signal peptide or a membrane-spanning region.
Gene: Protein-coding gene on chromosome 19 (7,728,957 to 7,733,906, reverse strand). Ensembl gene ENSG00000182566.
Subcellular location: Cell membrane
Pathways (Reactome):
Immune System: Immunoregulatory interactions between a Lymphoid and a non-Lymphoid cell
Gene Ontology:
Molecular function: carbohydrate derivative binding; D-mannose binding; fructose binding; protein binding; virus coreceptor activity; virus receptor activity; carbohydrate binding; glycosylated region protein binding; pattern recognition receptor activity; polysaccharide binding
Biological process: positive regulation of viral life cycle; symbiont entry into host cell; immune response
Cellular component: plasma membrane; external side of plasma membrane
Genetic constraint (gnomAD): Loss-of-function variants: 29 observed, 27.46 expected, observed/expected ratio (o/e) 1.06, 90% interval 0.79 to 1.44. The upper end of that interval is the gene's LOEUF score, 1.44, which puts it in group 5 of 6, group 1 being the genes least tolerant of losing a copy. Missense variants: 318 observed, 281.29 expected, observed/expected ratio (o/e) 1.13, 90% interval 1.03 to 1.24. Synonymous variants: 136 observed, 118.08 expected, observed/expected ratio (o/e) 1.15, 90% interval 1 to 1.33.
Homologues: Orthologues: chimpanzee CLEC4G (99% identical), macaque CLEC4G (94% identical), pig CLEC4G (71% identical), dog CLEC4G (71% identical), guinea pig CLEC4G (69% identical), mouse Clec4g (64% identical), rat Clec4g (63% identical), zebrafish asgr1a (18% identical), Drosophila melanogaster tfc (17% identical), tropical clawed frog clec4m (17% identical), tropical clawed frog asgr1 (17% identical), zebrafish asgr1c.2 (17% identical), and 16 more. Paralogues in human: CD209 (22% identical), CLEC4M (22% identical), CLEC17A (22% identical), CLEC4E (20% identical), CLEC4A (20% identical), ASGR1 (19% identical), CLEC10A (19% identical), FCER2 (19% identical), CLEC4D (19% identical), ASGR2 (18% identical), CD207 (18% identical), CLEC4F (18% identical), and 2 more.
Diseases named in the same sentence as CLEC4G in open-access papers:
CLEC4G is named in the same sentence as 41 diseases in open-access papers, as found by Europe PMC text mining. Sharing a sentence is not in itself a finding about the gene and the disease. The quoted sentences say what the papers report.
melanoma (8 papers, 2018 to 2024). A malignant, usually aggressive tumor composed of atypical, neoplastic melanocytes. "C-Type Lectin Domain Family 4 Member G (CLEC4G or LSECtin) is one such ligand that can be found in normal liver but has also been found on melanoma cells." (PMID 34068762, 2021).
breast carcinoma (6 papers, 2021 to 2025). "Compared with other cancers, CLEC4G expression in liver cancer shows a unique expression pattern: it is positively correlated with pathological stage in breast cancer and gastric cancer, but significantly affects the prognosis in lung cancer." (PMID 41395114, 2025).
hepatocellular carcinoma (5 papers, 2020 to 2025). A malignant tumor that arises from hepatocytes. "The objective was to analyze the effect of C-type lectin domain family 4 member G (CLEC4G) on hepatocellular carcinoma (HCC) and investigate its impact on lenvatinib (Lenva) resistance as well as the underlying action pathway." (PMID 41395114, 2025). "We found significantly higher mRNA levels of CLEC4A and CLEC4L in HCC tissues compared to normal liver tissues, whereas the expression of CLEC4G/H1/H2/M was significantly lower in liver carcinoma." (PMID 34409028, 2021). "Initially, a pair of key genes, namely CLEC4G and CLEC4M were found with significant difference between tumors and controls, when retrieved a public dataset (GSE104310) of hepatocellular carcinoma." (PMID 33123293, 2020). "Three genes, namely, CLEC4G, LCP2, ST8SIA1 are acting as biomarkers in liver carcinoma." (PMID 38674383, 2024).
Alzheimer disease (4 papers, 2023 to 2024). A progressive, neurodegenerative disease characterized by loss of function and death of nerve cells in several areas of the brain leading to loss of cognitive function such as memory and language. "Our study highlights the expression of CLEC4G in the brain, predominantly on neurons, and its potential role in Alzheimer’s disease (AD)." (PMID 38731839, 2024). "CLEC4G, a glycan-binding receptor, has previously been demonstrated to inhibit Aβ generation, yet its brain localization and functions in Alzheimer’s disease (AD) are not clear." (PMID 38731839, 2024).
liver cancer (4 papers, 2022 to 2025). An epithelial or non-epithelial malignant neoplasm that arises from the liver. "The results showed that the expression levels of CLEC4G in liver cancer were much higher than the expression levels in other cancer types." (PMID 37754250, 2023).
colitis (3 papers, 2020 to 2023). Inflammation of the colon. "Deficiency in LSECtin (Clec4g)‐dependent corpse clearance by macrophages and lack of NRBF2‐mediated efferocytosis result in serious epithelium damage and inflammatory response in an experimental colitis model." (PMID 37994307, 2023).
viral infection (3 papers, 2021 to 2024). "The C-type lectin CLEC4G (LSECtin) has a postulated role in viral infection of cells and interacts with envelope glycoproteins on Japanese encephalitis virus, lymphocytic choriomeningitis virus, ebolavirus, and SARS-CoV-1 spike glycoproteins." (PMID 36054185, 2022).
Stroke (2 papers, 2023 to 2025). Sudden impairment of blood flow to a part of the brain due to occlusion or rupture of an artery to the brain. "CLEC4G, alternatively known as liver and lymph node sinusoidal endothelial cell C-type lectin (LSECtin), was associated with stroke severity when measured by mRS." (PMID 37468969, 2023). "For example, CLEC4G has been identified as a novel inflammatory biomarker related to the severity of stroke." (PMID 41395114, 2025). "Higher relative concentrations of plasma CLEC4G, CKAP4, and IL-6 were associated with higher stroke severity, whereas LY75 and ITGA11 showed an inverse association." (PMID 37468969, 2023). "The biomarkers CLEC4G, CKAP4, IL6, LY75 and ITGA11 were found to be significantly associated with stroke severity as measured by mRS and in case of IL6 and ITGA11 also by NIHSS." (PMID 37468969, 2023). "The present study confirmed the positive associations between stroke severity and IL6 and CKAP4, but also elucidated novel associations, namely between CLEC4G, LY75 and ITGA11, which enrich the present knowledge of blood biomarkers associated with stroke." (PMID 37468969, 2023).
atopic dermatitis (1 paper, 2025). "For instance, CLEC4G participates in atopic dermatitis progression by activating functional proteins related to the immune system." (PMID 41395114, 2025).
influenza (1 paper, 2024). An acute viral infection of the respiratory tract, occurring in isolated cases, in epidemics, or in pandemics; it is caused by serologically different strains of viruses (influenzaviruses) designated A, B, and C, has a 3-day incubation period, and usually lasts for 3 to 10 days. "This discrepancy between the upregulation of CLEC4G by the influenza HA antigen and its downregulation by the SARS-CoV-2 S RBD peptide antigen warrant further investigation." (PMID 38932372, 2024).
liver fibrosis (1 paper, 2023). "In contrast to LyECs, Mcam, Fcgr2b (CD32b), Cxcl9, CD36, Kit, Clec4g, etc., genes were highly expressed in LSECs from CCl4-induced liver fibrosis, NASH and BDL mice." (PMID 36632228, 2023).
lung carcinoma (1 paper, 2025). "Research has indicated that CLEC4G can activate M2‐type macrophages, thus facilitating the immune escape of lung cancer cells." (PMID 41395114, 2025).
psoriasis (1 paper, 2014). An autoimmune condition characterized by red, well-delineated plaques with silvery scales that are usually on the extensor surfaces and scalp. "Namely, RHCG, TCN1, KLK6, and LCN2 were chosen for psoriasis and CCL17, NCF4, BATF3, and CLEC4G as ACD-specific genes." (PMID 25058585, 2014).
tumor (35 papers, 2018 to 2025). "Recent exploration of the relationship between the expression of CD34 and other molecular markers in HCC revealed an inverse correlation between the expression of CD34 and C-type Lectin Domain Family 4 Member G (CLEC4G) in HCC tumor tissues." (PMID 40941632, 2025). "That is to say, in the future, targeted silencing of CLEC4G expression can not only reverse the drug resistance of HCC cells to Lenva but also further promote the death of tumor cells, thus providing a more reliable guarantee for the treatment and prognosis of HCC patients." (PMID 41395114, 2025). "E-selectin, ICAM1 or Clec4g mediate tumor cell adhesion and thus facilitate liver metastasis." (PMID 36496412, 2022). "LAG-3 also interacts with Human LSECtin (liver and lymph node sinusoidal endothelial cell C-type lectin, CLEC4G), which is widely expressed on many tumor cell surfaces." (PMID 32640575, 2020). "During tumor metastasis, hepatic endothelial cells represent the first barrier interacting with arriving cancer cells via surface receptors like E-selectin, ICAM1 or Clec4g." (PMID 36496412, 2022). "However, the expression of CLEC4A, CLEC4D, CLEC4E, CLEC4J (FCER2), CLEC4K (CD207), CLEC4G, CLEC4H1, CLEC4M, and CLEC4H2 decreased with tumor progression." (PMID 34409028, 2021).
cancer (14 papers, 2019 to 2025). A tumor composed of atypical neoplastic, often pleomorphic cells that invade other tissues. "The heat map showed that 51 DEGs were expressed in cancer/paracancerous tissues, and the blue cluster area suggested that genes such as CLEC4G were significantly up‐regulated." (PMID 41395114, 2025). "In clinical samples, CLEC4G mRNA expression was seen to be higher in cancer tissues than in paracancerous tissues of HCC patients (p < 0.01), validating the results of the analysis of the appealing biological information." (PMID 41395114, 2025). "Ultimately, CLEC4G is a type II transmembrane protein expressed by APCs and certain types of cancer." (PMID 37215135, 2023). "CLEC4G which is an underexpressed gene in cancer is the chief performer with AUC ~0.99 at threshold 2.9; whereas PLVAP is overexpressed gene in cancer samples, it can distinguish samples with AUC 0.97 at threshold 3.8." (PMID 31490960, 2019).
infection (11 papers, 2013 to 2024). The state of being infected such as from the introduction of a foreign agent such as serum, vaccine, antigenic substance or organism. "Interestingly, we observed that after infection, CLEC4G, the putative receptor gene of SARS, was significantly downregulated in the lung of the PRRSV-infected pigs compared to the non-infected pigs." (PMID 35211513, 2022). "SARS-CoV utilizes ACE2, CD209, CLEC4G, and CLEC4M for its infection to host." (PMID 33330620, 2020). "Notably, EBOV has very broad cell tropism, especially later in the course of infection, and it may bind to multiple attachment factors, notable among which are numerous lectins (DC-SIGN/L-SIGN, MGL [CLEC10A], LSECtin [CLEC4G]) and Niemann-Pick C1 endosomal membrane protein." (PMID 23573288, 2013).
CLEC4G also shares sentences with these, for which no sentence is quoted: colon cancer (5 papers); gastric cancer (4); COVID-19 (3); cognitive decline (2); asthma (1); bladder cancer (1); cholangiocarcinoma (1); Chronic Lymphocytic Leukemia (1); chronic myelogenous leukemia (1); chronic sinusitis (1); Cirrhosis (1); colorectal carcinoma (1); Glycogen Storage Disease (1); head and neck squamous cell carcinoma (1); invasive breast carcinoma (1); Pancreatic Cancer (1); paraganglioma (1); pheochromocytoma (1); polyp (1); rhinitis (1); septic shock (1); stomach adenocarcinoma (1); uterine carcinosarcoma (1); viral hepatitis (1); Wilms tumor (1).